GBX1 (gastrulation brain homeobox 1)
Synonyms: Huh-17
Tractability: No criterion of Open Targets' tractability assessment is met for any kind of drug.
Gene: Protein-coding gene on chromosome 7 (151,148,009 to 151,174,745, reverse strand). Ensembl gene ENSG00000164900.
Subcellular location: Nucleus
Gene Ontology:
Molecular function: DNA-binding transcription factor activity, RNA polymerase II-specific; RNA polymerase II transcription regulatory region sequence-specific DNA binding; DNA binding
Biological process: regulation of nervous system development; regulation of transcription by RNA polymerase II; regulation of DNA-templated transcription
Cellular component: chromatin; nucleus
Genetic constraint (gnomAD): Loss-of-function variants: 9 observed, 20.44 expected, observed/expected ratio (o/e) 0.44, 90% interval 0.26 to 0.77. The upper end of that interval is the gene's LOEUF score, 0.77, which puts it in group 3 of 6, group 1 being the genes least tolerant of losing a copy. Missense variants: 494 observed, 458.68 expected, observed/expected ratio (o/e) 1.08, 90% interval 1 to 1.16. Synonymous variants: 203 observed, 194.65 expected, observed/expected ratio (o/e) 1.04, 90% interval 0.93 to 1.17.
Homologues: Orthologues: chimpanzee GBX1 (100% identical), macaque GBX1 (99% identical), dog GBX1 (98% identical), pig GBX1 (96% identical), rat Gbx1 (92% identical), mouse Gbx1 (91% identical), guinea pig GBX1 (62% identical), zebrafish gbx1 (62% identical), tropical clawed frog GBX1 (57% identical), Drosophila melanogaster unpg (39% identical). Paralogues in human: GBX2 (49% identical).
Diseases named in the same sentence as GBX1 in open-access papers:
GBX1 is named in the same sentence as 9 diseases in open-access papers, as found by Europe PMC text mining. Sharing a sentence is not in itself a finding about the gene and the disease. The quoted sentences say what the papers report.
developmental delay (1 paper, 2025). "Our finding of a GBX1 gene variant is novel; we first identified a GBX1 variant associated with developmental delay and focal epilepsy." (PMID 40519143, 2025).
epilepsy (1 paper, 2025). A brain disorder characterized by episodes of abnormally increased neuronal discharge resulting in transient episodes of sensory or motor neurological dysfunction, or psychic dysfunction. "Moreover, a correlation is demonstrated between the GBX1 mutation and the occurrence of epilepsy in the zebrafish model." (PMID 40519143, 2025). "While our zebrafish gbx1 crispant model provides valuable insights into the role of gbx1 in neurodevelopment and epilepsy, it is essential to acknowledge that animal models may not fully replicate the complexity of human neurological disorders." (PMID 40519143, 2025).
focal epilepsy (1 paper, 2025). A seizure caused by a localized disorder. "We first identified an association between the GBX1 gene variant and focal epilepsy, and observed related phenotypes in the gbx1‐Cas9 zebrafish model." (PMID 40519143, 2025). "Our study is the first to identify an association between the GBX1 gene variant and focal epilepsy." (PMID 40519143, 2025). "Subsequent WES identified a de novo heterozygous variant in the GBX1 gene, which may be the cause of her focal epilepsy." (PMID 40519143, 2025).
GBX1 also shares sentences with these, for which no sentence is quoted: Alzheimer disease (1 paper); attention deficit/hyperactive disorder (1); insulinoma (1); neurological disorders (1); post-traumatic stress disorder (1); resistant hypertension (1).